CTLA4 (cytotoxic T-lymphocyte associated protein 4)
Diseases named in the same sentence as CTLA4 in open-access papers (continued):
Sharing a sentence is not in itself a finding about the gene and the disease.
systemic lupus erythematosus (63 papers, 2009 to 2025). An autoimmune multi-organ disease typically associated with vasculopathy and autoantibody production. "Data suggest that both PD1 and CTLA4 gene polymorphisms in humans and deficiencies in animal models can lead to lupus manifestations." (PMID 32403289, 2020). "For example, an increased risk of systemic lupus erythematosus (OR = 1.19) was observed when CTLA4 (cytotoxic T lymphocyte antigen 4), a negative regulator of T cell response interacts with SNPs rs3131379 and rs1270942 located in the HLA class III region." (PMID 30060490, 2018). "Similarly, the low expression of CTLA4 in Foxp3+CD25+CD4+ Tregs has been negatively associated with disease activity in patients with systemic lupus erythematosus." (PMID 39284778, 2024). "CTLA-4 is a T-cell-specific protein receptor implicated in lupus development and activity." (PMID 38399467, 2024). "Accumulating evidences suggested that CTLA-4 rs733618 T>C polymorphism might be associated with the increased risk of systemic lupus erythematosus." (PMID 29100337, 2017). "Several meta-analyses showed that CTLA-4 -1722T/C polymorphism might be a risk factor for systemic lupus erythematosus susceptibility." (PMID 24710335, 2014). "In animal models, anti-CTLA4 drugs induce major depletion of regulatory T cells, and mouse model of anti-PD-1 deletion resulted in lupus-like proliferative arthritis and glomerulonephritis." (PMID 39225744, 2024). "In immune checkpoint blockade therapy, target against CTLA-4 induces immune-related adverse events including lupus-like glomerulonephritis." (PMID 34736521, 2021). "This study found a correlation between CD38 with FoxP3 expression and immunosuppressive molecules (CD69, IL-10, CTLA-4, and PD-1) in T-cells from lupus-prone mice (B6.MRL-Faslpr/J)." (PMID 34769406, 2021). "High sCTLA-4 serum levels have previously been identified in lupus patients, and low efficiency of production was mooted to be associated with a susceptibility CT60 SNP genotype of CTLA-4." (PMID 27487771, 2016). "However, trial data also showed increased acute cellular rejection within the first-year post-transplant, with other reports linking CTLA-4 inhibitors with new onset psoriasis and chilblain lupus." (PMID 36598752, 2023). "However, another study reported that mTORC1 inhibitor-induced autophagy restores CTLA-4 expression and corrects Treg cell function in systemic lupus erythematosus (SLE)." (PMID 36230955, 2022). "Considering that CTLA-4 is an essential molecule for immunological tolerance, a phenotypic dysregulation of CTLA-4+ iTreg cells in allergic subjects, similar to that described in patients with systemic lupus erythematosus, could be considered." (PMID 35878164, 2022). "Moreover, CTLA-4–Fc has been proven to be highly effective in mouse models of lupus." (PMID 31597242, 2019). "Here, we investigate cytokine responses to a range of lupus-associated autoantigens and assess whether the alternatively spliced isoform of CTLA-4, soluble CTLA-4 (sCTLA-4), contributes to immune regulation of autoantigen-specific immunity in systemic lupus erythematosus (SLE)." (PMID 27487771, 2016). "The expression of a number of co-stimulatory molecules, such as CTLA-4/CD152, and soluble mediators, such as BAFF/BLyS, a critical survival factor for transitional and mature B cells, is also dysregulated in lupus." (PMID 34744730, 2021). "Relatedly, the in vitro treatment of splenocytes from lupus-prone BXSB mice with OX40L mAb, in combination with an anti-CTLA-4 strategy, suppresses autoantibody production and pro-inflammatory cytokines." (PMID 31597242, 2019).
liver cancer (62 papers, 2016 to 2025). An epithelial or non-epithelial malignant neoplasm that arises from the liver. "The involvement of immunological checkpoint proteins such as programmed cell death protein-1 (PD-1) and cytotoxic T lymphocyte-associated antigen 4 (CTLA-4) in liver cancer is becoming increasingly well-known." (PMID 38890507, 2024). "A combination of anti the programmed cell death protein 1/programmed cell death ligand 1 (PD-1/PD-L1) and anti-cytotoxic T-lymphocyte-associated protein 4 (CTLA-4) antibodies is currently being evaluated in clinical trials for liver cancer." (PMID 39583200, 2024). "For instance, in liver cancer, Tregs frequently express high levels of Programmed Death-Ligand 1 (PD-L1) and Cytotoxic T-lymphocyte-associated protein 4 (CTLA4)." (PMID 39136031, 2024). "Our study found that liver cancer patients in the high-risk group had high expression of some immune checkpoints (PD-1, PD-L1, CTLA4, B7-H3, VSIA, LAG3 and TIGIT)." (PMID 36081999, 2022). "However, due to the immunosuppressive microenvironment of liver cancer, conventional immune checkpoint inhibitors, such as programmed death 1 (PD-1) and cytotoxic T lymphocyte-associated antigen 4 (CTLA-4), have limited therapeutic effects for liver cancer." (PMID 34257558, 2021). "The combination of PD-1 inhibitors and CTLA-4 inhibitors (such as nabuliumab combined with ipilimumab) had shown a synergistic effect in advanced liver cancer." (PMID 40276056, 2025). "Immune checkpoint inhibitors targeting CTLA4 and PD-1/PD-L1 have become standard treatment for advanced liver cancer." (PMID 41321947, 2025). "The data presented here demonstrated that Th1 play an important role in the pharmacological mechanism of anti-CTLA-4 Ab-mediated actions in a liver cancer model." (PMID 39106430, 2024). "We compared the expression differences of two common immune checkpoint proteins, PD-1 and CTLA-4, between the HR and LR groups in liver cancer and found that their expression was higher in the HR group." (PMID 38907744, 2024). "CTLA-4 enhances the antitumor effect of effector T cells, maintains self-tolerance, and suppresses the function of Tregs in liver cancer immunity." (PMID 38409471, 2024). "By targeting these molecules, inhibitors such as anti-CTLA4, anti-PD-1, and anti-PD-L1 antibodies demonstrate potential in liver cancer immunotherapy, as they block immunosuppressive signals and reactivate anti-tumor immune responses." (PMID 37600802, 2023). "In recent years, the discovery of immune checkpoints such as PD-1, PD-L1 and CTLA4 and the development and application of corresponding immune checkpoint inhibitors have provided new options for the treatment of advanced liver cancer." (PMID 37858061, 2023). "LncRNA MIAT is positively correlated with immune checkpoint molecules, such as PD-1 and CTLA4, in liver cancer cells." (PMID 36755568, 2023). "At the same time, studies have shown that immunotherapy with anti PDCD1 and anti CTLA-4 antibodies is effective in the treatment of advanced liver cancer." (PMID 37081394, 2023). "Multiple immune mechanisms such as checkpoint inhibition targeting PD-1, PD-L1, and CTLA-4 have been shown to be effective, tolerable, and clinically beneficial for advanced liver cancer." (PMID 37670307, 2023). "Although immune checkpoint inhibitors (ICIs) including anti-PD-1 and anti-CTLA-4 are becoming standard of care in various cancers, including other forms of liver cancer, few studies have examined the safety and efficacy of ICIs in FLC." (PMID 36358766, 2022). "Recent studies have recognized that the overexpression of immune checkpoints, such as PD‐L1, CTLA4, and LAG3, is associated with poor prognosis in liver cancer, which is consistent with our result of the Lnc_high group having poor DFS and OS." (PMID 35040184, 2022). "It is indicated that patients with liver cancer stratified by TIMSig and PD-L1 or CTLA-4 exhibited OS analogous to PD-1." (PMID 36120553, 2022).
liver cancer (continued). "Most patients in both single-cell transcriptome datasets received PD-1 or PD-L1/CTLA-4 monoclonal antibody therapy and predominantly exhibited stage IV liver cancer development." (PMID 36569894, 2022). "These important findings suggest that the internal environment of SD exosome CTLA-4 promotes the metastasis of liver cancer by regulating the PTEN/CD44 pathway." (PMID 34744733, 2021). "The results of immunohistochemistry and WB (Western Blot) showed that both the SD group and liver cancer group mice had significantly higher (p < 0.01) levels of CTLA-4 and PD-1 compared with the normal group." (PMID 34744733, 2021). "Briefly, 10 μl of PBS, liver cancer mouse serum, SD liver cancer mouse serum, SD liver cancer mouse serum plus CTLA-4 inhibitors were added separately into a 96-well plate with HepG2 cells." (PMID 34744733, 2021). "In this study, double-stranded interference RNA (siRNA) is applied to inhibit the expression of PD-1 and CTLA-4 to study the feasibility of siRNA as a therapeutic for liver cancer." (PMID 30564277, 2018). "Immune checkpoint blockade with antibodies targeting B7 immunoglobulin superfamily molecules such as CTLA-4, PD-1, and PD-L1 is showing promising clinical activity in multiple GI tumors including esophageal, gastric, colorectal, and liver cancers." (PMID 28434400, 2017). "The data may provide insights into why liver cancer patients, where fibrosis is often present, may respond suboptimally to PD‐1 or CTLA‐4 immunotherapy." (PMID 40760842, 2025). "The mechanism of immune checkpoint inhibitors: Immune checkpoint inhibitors such as PD-1 inhibitors and CTLA-4 inhibitors can block the signaling of immune checkpoint receptors on the surface of liver cancer cells and their ligands, restoring the activation and attacking capability of immune cells." (PMID 37880661, 2023). "PD-1 and CTLA-4 were gradually used for immune checkpoint inhibitors to treat liver cancer." (PMID 35938165, 2022). "The TICA database data showed that liver cancer patients within the low EM score group had higher sensitivity to CTLA4 inhibitors (p = 0.00015), PD-1 inhibitors (p = 0.0021), and PD-1 inhibitors combined with CTLA4 inhibitors (p = 0.0066)." (PMID 35602603, 2022). "Previous reports indicate that liver cancer tissues are characterized with a high expression level of PD-L1, CTLA4, lymphocyte activation gene 3, and other immunosuppressive molecules, which is negatively associated with the tumour infiltration of IFNγ+ T lymphocytes." (PMID 35574316, 2022). "Detecting apoptosis on HepG2 cells showed that SD-HCC mice serum can induce the least cell apoptosis compared with liver cancer mouse serum and when added into CTLA-4 inhibitors could partially reverse cells apoptosis." (PMID 34744733, 2021). "Studies have shown that tumor-specific cytotoxic T cells in primary liver cancer are accompanied by high expression of inhibitory immune checkpoints such as CTLA4, PD-L1 and TIM3, which makes T cells unable to effectively recognize tumor cells and lead to immune escape." (PMID 34266388, 2021). "In addition, the liver cancer mice with SD had significantly higher levels of CTLA-4 and PD-1 proteins than those in the liver cancer group only (p < 0.01)." (PMID 34744733, 2021). "Some miRNAs and lncRNAs might be involved in the “cancer immunity cycle” regulated by immune checkpoints such as CTLA-4 and PD-L1-PD-1 and could be the subject of future investigations in liver cancer." (PMID 29843754, 2018). "Moreover, the FDA also accelerated approval of the anti-PD-1 antibody pembrolizumab as monotherapy and a combination of nivolumab (another anti-PD-1 antibody) and ipilimumab (an anti-ctLA4 antibody) for second-line treatment of advanced liver cancer, based on efficacy data from early trials." (PMID 37670307, 2023). "Furthermore, EV-derived CTLA-4 promotes proliferation and metastasis in liver cancer." (PMID 37884996, 2023).
liver cancer (continued). "Interestingly, a combined treatment with the MMP inhibitor and anti-CTLA-4 antibody could delay tumor growth and reduce the metastases compared with anti-CTLA-4 treatment alone in lung and liver cancers." (PMID 36230852, 2022). "In addition, the immunotherapy of anti-CTLA4 has been widely used in the treatment of liver cancer." (PMID 34901153, 2021). "Thus, CTLA-4 could not only enhance the antitumor effect of effector T cells but also maintain self-tolerance and the suppressive function of Tregs in liver cancer immunity." (PMID 29843754, 2018). "Within the microenvironment of liver cancer cells, CENP‐F also positively correlates with inhibitory checkpoint molecules such as PD‐1, CTLA‐4, and TIM‐3, suggesting its involvement in the weakening of anti‐tumor immunity in liver cancer cells." (PMID 40387105, 2025). "In order to identify novel immune biomarkers from the TCGA-LIHC and examine associated expression with established immune biomarkers for T cell activation with an immune checkpoint inhibitor in liver cancer, this study examined PDCD1, CTLA4, HAVCR2, and LAG3." (PMID 38248311, 2023). "In conclusion, our findings suggest that during SD in the internal environment, exosome CTLA-4 regulates the PTEN/CD44 signal pathway to promote the proliferation, self-renewal, and metastasis of liver cancer." (PMID 34744733, 2021). "In addition, the research on new immune checkpoints such as FGL1, CTLA-4, TIM-3, and LAG-3 were also constantly advancing, providing more possibilities for liver cancer immunotherapy." (PMID 40276056, 2025). "The mRNA expression levels of immune checkpoint-related genes were significantly higher in the high-risk group than in the low-risk group, especially for immune checkpoint-related genes commonly used in liver cancer immunotherapy, including (PD-L1, PDCD1LG2, PDCD1, TIGIT, TIM-3, CTLA4)." (PMID 36814910, 2023). "Anti‐CTLA‐4: Tremelimumab (3.5 or 10 mg/kg, per 4 weeks) was administered intravenously.Ablation: Radiofrequency or cryotherapy ablation was performed 36 days after initial ICI medication.TACE: Patients with Barcelona Clinic Liver Cancer (BCLC) Stage B received TACE in conjunction with ablation." (PMID 35908281, 2022). "Our previous study found that traditional Chinese medicine could improve the tumor microenvironment of patients to treat liver cancer and speculated that the immune checkpoints CTLA-4, LAG-3, and BIRC5 are the key targets for activating immune cells to treat liver cancer." (PMID 34744733, 2021).
head and neck squamous cell carcinoma (61 papers, 2016 to 2025). A squamous cell carcinoma that arises from any of the following anatomic sites: lip and oral cavity, nasal cavity, paranasal sinuses, pharynx, larynx, and salivary glands. "In head and neck squamous cell carcinoma, dasatinib acted synergistically with cytotoxic T-lymphocyte associated protein 4 (CTLA4) blockade, suggesting yet another avenue of investigation." (PMID 32664483, 2020). "Dual blockade of CTLA-4 and PD-1 is currently being evaluated in numerous clinical trials for advanced solid tumors, such as head and neck squamous cell carcinoma (HNSCC) and glioblastomas (NCT04080804, NCT04606316)." (PMID 37928556, 2023). "A notable advance in the treatment of head and neck squamous cell carcinoma (HNSCC) in recent years has been the development of immunotherapy with immune checkpoint inhibitors (ICIs) using anti-CTLA-4, anti-PD-1, and anti-PD-L1 antibodies." (PMID 35159059, 2022). "Another homologous recombination gene, XRCC3, was identified to correlate with CTLA4 expression in all three cancer types but exceeded the cutoff for CD274 only in head and neck squamous cell carcinoma." (PMID 27683114, 2016). "A positive ICOS signature may indicate a better clinical outcome of anti-CTLA-4 immune therapy in HPV-positive head and neck squamous cell carcinoma and EBV-positive stomach adenocarcinoma patients." (PMID 30911684, 2019). "Additionally, patients with head and neck squamous cell carcinomas have also been shown to have increased levels of the CTLA-4+ on Tregs when compared to healthy donors." (PMID 28936253, 2016). "In the context of oral squamous cell carcinoma (OSCC) and broader head and neck squamous cell carcinoma (HNSCC), agents such as pembrolizumab, durvalumab, and ipilimumab target PD-1, PD-L1, and CTLA-4, respectively." (PMID 40940902, 2025). "In an interesting series of observations, the Authors initially reported that regulatory T (Treg) cells expressing CTLA‐4 on the cell surface are abundant in head and neck squamous cell carcinoma (HNSCC)." (PMID 40836971, 2024). "In a mouse model of head and neck squamous cell carcinoma (HNSCC), combining anti-CTLA4 immunotherapy with the inhibition of Src family kinases (SFKs) showed a synergistic reduction in tumor growth." (PMID 38931856, 2024). "Compared with single use either alone, combined therapy with TH-302 and an anti-CTLA-4 Ab augments CTLA-4 blockade in a head and neck squamous cell carcinoma (HNSCC) model; and further improves the survival of HNSCC patients." (PMID 38481819, 2024). "In particular, the advent of ICI, that block PD-1, PD-L1 and CTLA-4, significantly improved treatment for a number of solid tumors, such as metastatic melanoma, non-small-cell lung cancer, merkel cell carcinoma, colon carcinoma, head-and-neck squamous cell carcinoma (HNSCC) and others." (PMID 35693776, 2022). "In a murine model of head and neck squamous cell carcinoma (HNSCC), the blockade of CTLA-4 was correlated with reduced numbers of MDSCs and M2 macrophages, and enhancement of T-cell activation in both tumor microenvironment and macro-environment." (PMID 32656079, 2020). "In head and neck squamous cell carcinoma (HNSCC), a low infiltration of PD-1 expressing lymphocytes and high CTLA-4 tumor expression was found to be significantly correlated with a poor prognosis as well as in the HPV− cohort." (PMID 32635549, 2020). "Additional phase Ib/II studies of anti-SEMA4D in combination with anti-PD-L1 and/or anti-CTLA-4 for treatment of melanoma and head and neck squamous cell carcinoma (HNSCC) are anticipated." (PMID 28649381, 2017). "Combined CTLA4 and VISTA blockade treatment was more efficient than PD1 and VISTA blockade in head and neck squamous cell carcinoma models." (PMID 38634058, 2024). "In head and neck squamous cell carcinoma (HNSCC), the overexpression of let-7a/b miRNAs in combination with CTLA-4 antibody promotes anticancer immunity by accelerating PD-L1 degradation." (PMID 34572067, 2021).